MCM8 (minichromosome maintenance 8 homologous recombination repair factor)
Diseases named in the same sentence as MCM8 in open-access papers (continued):
Sharing a sentence is not in itself a finding about the gene and the disease.
Infertility (4 papers, 2022 to 2026). "In mice, the mini-chromosome maintenance family protein, MCM8, has been proposed to function in meiotic recombination and its loss leads to infertility, but the underlying mechanisms are poorly understood." (PMID 41959065, 2026). "Taken together, our findings demonstrated that profound PGC loss was a key reason for the infertility of Mcm8 KO mice." (PMID 38858601, 2024). "Thus, the loss of meiotic germ cells is considered to be a leading cause of infertility in Mcm8-null mice and individuals." (PMID 38858601, 2024). "Because of the high conservation of MCM8 between humans and mice, our findings support the hypothesis that infertility in individuals with MCM8 loss-of-function variants is due to PGC deficiency." (PMID 38858601, 2024). "Our findings extend our understanding of the function of MCM8 in germ cell development and the pathogenesis of MCM8-related infertility, and also give insights into the regulatory network involved in the maintenance of genome stability in mitotic germ cells." (PMID 38858601, 2024). "Among these mutated infertility genes, mutations of FSIP2, CFAP69, CEP19, MSH5 or MCM8 are recessive for spermatogenic failure or premature ovarian insufficiency." (PMID 35547809, 2022). "Mutations in MCM8 and MCM9 have been clearly linked with infertility and primary ovarian insufficiency as well as predispositions to a variety of cancers." (PMID 36042199, 2022). "Thus, we revealed a new explanation for the infertility induced by these MCM8 mutants." (PMID 38858601, 2024). "DNA damage induced by increased R-loops after disabling MCM8 may contribute to PGC proliferation defects and infertility." (PMID 38858601, 2024). "Indeed, both mice and humans with non-functional MCM8/9 display reproductive system abnormalities including infertility, sex-specific tumor formation, sensitivity to DNA damaging agents, and defects in HR processing." (PMID 36042199, 2022).
lung carcinoma (4 papers, 2019 to 2025). "MCM8 is a helicase, which participates in DNA replication and tumorigenesis and is upregulated in many human cancers, including lung cancer (LC); however, the function of MCM8 in LC tumour progression is unclear." (PMID 39031896, 2024). "GSEA for different expression levels of MCM4, MCM5 and MCM8 indicated that significant correlation of the genes with lung cancer progression and survival." (PMID 31323040, 2019).
premature ovarian failure (4 papers, 2015 to 2024). "For example, MCM8 mutation leads to defects in chromosome breakage and repair of fibroblasts in the premature ovarian failure." (PMID 38988047, 2024). "In the present study, a variant of the MCM8 gene was investigated in women with primary ovarian insufficiency to elucidate the role of MCM8 in this pathology." (PMID 39607112, 2024). "A cancer-derived point mutation or an SNP on MCM8 associated with premature ovarian failure (POF) diminishes the functional activity of MCM8." (PMID 26215093, 2015). "Considering the main role of MCM8 in the development and maintenance of gonads, our findings may contribute to elucidating the role of this variant in women with primary ovarian insufficiency." (PMID 39607112, 2024). "The MCM8-9 helicase functions during prophase I, which explains the studies relating the MCM8 gene to premature ovarian failure." (PMID 39607112, 2024). "The MCM8 gene variant was analyzed via real-time polymerase chain reaction using a hydrolysis probe in DNA samples from women diagnosed with primary ovarian insufficiency, with a normal karyotype and without FMR1 gene permutation, and from a Control Group, who had menopause after 50 years of age." (PMID 39607112, 2024).
Premature ovarian insufficiency (4 papers, 2021 to 2024). Amenorrhea due to loss of ovarian function before the age of 40. "Cells expressing premature ovarian insufficiency-causative mutants of MCM8 with decreased interaction with DDX5 displayed increased R-loop levels." (PMID 38858601, 2024). "We evaluated the frequency of the NG_042869.1:g.40270G>A (rs138761187) variant in MCM8 in Brazilian women with premature ovarian insufficiency and in those with normal menopause age." (PMID 39607112, 2024). "This cross-sectional, case-control study demonstrated that the MCM8 gene might be an autosomal gene implicated in premature ovarian insufficiency." (PMID 39607112, 2024). "So far, large-scale GWAS have identified several SNPs, such as rs11668344 (BRSK1), rs365132 (UIMC1) and rs16991615 (MCM8), relevant for age at natural menopause or premature ovarian insufficiency (POI) in the general population." (PMID 34572825, 2021).
Azoospermia (3 papers, 2019 to 2025). Absence of any measurable level of sperm,whereby spermatozoa cannot be observed even after centrifugation of the semen pellet. "Biallelic mutations in two other DNA DBS repair genes, MCM8 and TEX15 were reported in azoospermia and oligo/crypto/azoospermia, respectively." (PMID 34501457, 2021). "Apart from five males (three with biallelic MCM8 variants and two with biallelic MCM9 variants) with azoospermia (no sperm in the semen; HP:0000027), these issues involved women affected by POI." (PMID 40684266, 2025).
bladder cancer (3 papers, 2021 to 2025). "To summarize, we reasoned that MCM8 was extensively associated with the development, progression and prognosis of bladder cancer." (PMID 33931059, 2021). "Given our findings and present studies, one could conclude that MCM8 was involved in the development, progression and prognosis of bladder cancer, which implicated the potential of MCM8 as a promising therapeutic target in bladder cancer." (PMID 33931059, 2021). "MCM8 have been found to be aberrantly expressed in a variety of malignancies including gastric cancer, cholangiocarcinoma, glioblastomas, bladder cancer, osteosarcoma and myeloid tumors." (PMID 36575045, 2022). "The in vivo experiments were conducted to verify the effects of MCM8 knockdown on the tumor growth of bladder cancer." (PMID 33931059, 2021). "Taken together, our study demonstrated an important role of MCM8 in bladder cancer and created a rationale for the therapeutic potential of MCM8 inhibition in human bladder cancer therapy." (PMID 33931059, 2021). "Initial analyses in the present study indicated that the expression level of MCM8 was up-regulated in bladder cancer and positively related to the advanced pathological grade and poor prognosis." (PMID 33931059, 2021). "The present study, we aimed at probing into the impacts and detailed mechanisms of MCM8 in bladder cancer progression." (PMID 33931059, 2021). "In conclusion, our collective findings demonstrated that MCM8 inhibition contributed to the suppression of bladder cancer tumorigenesis, laying the groundwork for potential therapeutic target to curb carcinogenesis." (PMID 33931059, 2021). "Taken together, these results showed that silencing of MCM8 arrested the cell cycle of bladder cancer cells while accelerating their apoptosis." (PMID 33931059, 2021). "The results demonstrated that compared with normal adjacent tissues, MCM8 expression in bladder cancer tissues was strongly up-regulated." (PMID 33931059, 2021). "As such, it could be speculated that the anti-tumorigenic effects of MCM8 inhibition on bladder cancer was primarily mediated by those proteins." (PMID 33931059, 2021). "In order to evaluate the biological implications of MCM8 in bladder cancer progression, T24 cells were transfected with RNAi targeting MCM8 (RNAi-11106, RNAi-11107, RNAi-11108), three of which successfully reduced the expression of MCM8 as evidenced by qRT-PCR analysis, especially RNAi-11108." (PMID 33931059, 2021). "Of note, MCM8 inhibition modulated the malignant phenotypes of bladder cancer cells." (PMID 33931059, 2021). "Here we demonstrated that MCM8 was up-regulated in bladder cancer." (PMID 33931059, 2021). "Unfortunately, little is known concerning the roles of MCM8 in bladder cancer." (PMID 33931059, 2021). "The up-regulation of MCM8 expression in bladder cancer may be a valuable independent prognostic indicator." (PMID 33931059, 2021). "Thus, this study was aimed to explore the roles of MCM8 in bladder cancer." (PMID 33931059, 2021). "Besides, the mechanism of the effects of MCM8 knockdown on bladder cancer was initially explored." (PMID 33931059, 2021). "However, the influence of MCM8 on bladder cancer remains far from being fully elucidated." (PMID 33931059, 2021). "Furthermore, inhibition of MCM8 in human bladder cancer cell lines EJ and T24 decreased cell proliferation and migration, as well as induced apoptosis, indicating that MCM8 might be a potential therapeutic target in bladder cancer." (PMID 33931059, 2021). "However, the specific molecular mechanism of MCM8 in bladder cancer has not been thoroughly understood." (PMID 33931059, 2021).
colorectal cancer (3 papers, 2023 to 2025). A primary or metastatic malignant neoplasm that affects the colon or rectum. "In this study, we comprehensively performed a number of molecular biology research technologies to reveal the expression pattern of MCM8 in colorectal cancer and its effect on the progression of colorectal cancer in vitro or in vivo." (PMID 37710286, 2023).
lymph node metastasis (3 papers, 2024 to 2025). "Further, MCM8 upregulation was associated with advanced tumour grade and lymph node metastasis, and indicated poor prognosis." (PMID 39031896, 2024). "According to the Mann–Whitney U and Spearman correlation analysis, MCM8 expression was positively correlated with T infiltrate, lymph node metastasis N, AJCC stage, and pathological grade." (PMID 38988047, 2024).
Primary amenorrhea (3 papers, 2024). "However, carriers with MCM8 loss-of-function homozygous variants display gonadal dysgenesis, presenting as invisible or very small ovaries and primary amenorrhea in POI patients and as Sertoli-cell-only syndrome instead of spermatogenic arrest at the meiotic stage in NOA patients." (PMID 38858601, 2024). "This could be explained by the fact that pathogenic variants in these genes (for instance STAG3, MCM8 or PSMC3IP) result most often in severe changes in the maintenance of the ovarian reserve and cause a rapid loss of ovarian function, resulting in POI and primary amenorrhea." (PMID 39595984, 2024).
prostate carcinoma (3 papers, 2015 to 2021). A carcinoma that arises from epithelial cells of the prostate gland. "Existing study elucidated that MCM8 amplification and overexpression underlined the aggressiveness of prostate cancer." (PMID 33931059, 2021). "The expression level of the MCM9 protein is correlated to the cisplatin resistance of some prostate cancer cell lines and a cancer-derived mutation of MCM8 inactivated MCM8." (PMID 26215093, 2015). "The cyclin D1/MCM8 interaction is required for Rb phosphorylation and S-phase entry in prostate cancer cells." (PMID 29285216, 2017).
cholangiocarcinoma (2 papers, 2023 to 2024). A carcinoma that arises from the intrahepatic biliary tree (intrahepatic cholangiocarcinoma) or from the junction, or adjacent to the junction, of the right and left hepatic ducts (hilar cholangiocarcinoma). "Additionally, a differential expression analysis of these genes based on cholangiocarcinoma and normal tissues samples from the TCGA database revealed significant upregulation of CDCA5, FAM111B, MCM8 and PCNA in cholangiocarcinoma, supporting their relevance in this context." (PMID 38687509, 2024).
chronic myelogenous leukaemia (2 papers, 2020 to 2021). "MCM8 was found to be helpful in treating patients with chronic myelogenous leukemia." (PMID 34490114, 2021).
colon cancer (2 papers, 2020 to 2025). "The copy number of MCM8 reached 16 copies per genome in some samples of breast and colon cancer; the MCM8 gene amplification was also detected in epithelial-mesenchymal transition, recruitment of a more substantial proportion of cells into proliferation cycle and gain of aggressive features." (PMID 32089988, 2020).
Fanconi anemia (2 papers, 2021 to 2024). Fanconi anemia (FA) is a hereditary DNA repair disorder characterized by progressive pancytopenia with bone marrow failure, variable congenital malformations and predisposition to develop hematological or solid tumors. "In LXF-289 cells, the NHEJ and Fanconi anemia pathways were strongly represented among the top hits enriched, as well as MCM8, MCM9, and HROB, genes that have previously been implicated in HR." (PMID 33788831, 2021). "It has been reported that the MCM8/9 complex participates in interstrand crosslink repair by functioning in RAD51-dependent HR repair downstream of the Fanconi anemia (FA) pathway, and Mcm8 and Mcm9 KO mice share the similar phenotype with FA-null mice of massive loss of proliferating PGCs." (PMID 38858601, 2024).
female infertility (2 papers, 2019 to 2025). Diminished or absent ability of a female to achieve conception. "Both MCM8 and BRCA2 have been shown to be associated with meiosis and female infertility, and STAG3 is a meiosis-specific gene involved in female infertility." (PMID 31803224, 2019). "Among the 110 biallelic MCM8 variant carriers in the 200000 UK Biobank, 2 individuals (1.8%) were registered with CRC, 3 (2.7%) with colonic polyps, 4 (3.6%) with adenomas, 1 (0.9%) with female infertility, and 6 (5.5%) with hypothyroidism." (PMID 40684266, 2025).
lung squamous cell carcinoma (2 papers, 2015 to 2022). "Finally, we turned to a lung squamous cell carcinoma in CBioPortal, with a point mutation that changed proline 456 in the WA motif of MCM8 to alanine." (PMID 26215093, 2015).
Lynch like-syndrome (2 papers, 2020 to 2021). "MCM8 (mini-chromosome maintenance 8 homologous recombination repair factor) germline mutations were recently associated with early-onset Lynch like-syndrome." (PMID 33672345, 2021). "MCM8 may be involved in germline predisposition to colorectal cancer in Lynch-like syndrome cases." (PMID 32841224, 2020).
melanoma (2 papers, 2021 to 2025). A malignant, usually aggressive tumor composed of atypical, neoplastic melanocytes. "MCM8 also was associated with immune cell infiltration in patients with melanoma, which may provide novel insights for the diagnosis and treatment of malignant melanoma." (PMID 34490114, 2021). "Except for MCM7, MCM1–6 and MCM8–10 were all highly expressed in metastatic melanoma than in primary melanoma in the TCGA cohort (P < 0.05)." (PMID 34490114, 2021).
non-small cell lung carcinoma (2 papers, 2021 to 2025). A group of at least three distinct histological types of lung cancer, including non-small cell squamous cell carcinoma, adenocarcinoma, and large cell carcinoma. "IFT57 exerts an oncogenic role in non-small cell lung cancer by activating DNA replication and cell cycle pathways via upregulation of MCM2, MCM6, and MCM8 expression." (PMID 40145017, 2025).
ovarian failure (2 papers, 2023 to 2024). "Studies have reported MCM8 gene suppression with primary ovarian insufficiency." (PMID 39607112, 2024). "In vitro analyses in the same study showed that MCM8 knockout results in small gonads and disrupted follicle development, so may be related to the primary ovarian insufficiency phenotype." (PMID 38737775, 2023).
ovarian tumors (2 papers, 2015 to 2022). "MCM8-MCM9-deficient mice exhibit gametogenesis deficiency, and MCM8 knockout female mice develop ovarian tumors, although MCM8/9-knockout mice are viable." (PMID 36032672, 2022).
pancreatic cancer (2 papers, 2018 to 2021). "More importantly, the up-regulation of MCM8 was regarded as a valuable independent prognostic indicator in patients with pancreatic cancer, suggesting a shorter overall survival time." (PMID 33931059, 2021). "MCM8 has been shown to have a significant regulatory relationship with the prognosis and survival of pancreatic cancer." (PMID 30521536, 2018). "MCM8 is involved in the regulation of DNA synthesis, regulating cell division in S phase, and has been shown to have a significant regulatory relationship with the prognosis and survival of pancreatic cancer." (PMID 30521536, 2018).
autoimmune thyroid disease (1 paper, 2022). Inflammatory disease of the thyroid gland due to autoimmune responses leading to lymphocytic infiltration of the gland. "Meanwhile, the low MCM8 expression data sets enriched mainly in MAPK signaling pathway, B cell receptor signaling pathway, Autoimmune thyroid disease, T cell receptor signaling pathway, etc.." (PMID 36575045, 2022).
clear cell renal carcinoma (1 paper, 2023). A malignant epithelial neoplasm of the kidney characterized by the presence of lipid-containing clear cells within a vascular network. "For example, MCM8 and CCNA1, two cell cycle genes that are normally downregulated in clear cell renal carcinoma Caki-1/2 cells after exogenous PBRM1 expression, were significantly upregulated in PBRM1 knockdown cells that expressed PBRM1-BAHmut compared with PBRM1-BAHwt." (PMID 37394010, 2023).
endometrial cancer (1 paper, 2025). Primary or metastatic malignant neoplasm involving the endometrium (mucous membrane that lines the endometrial cavity). "No biallelic MCM8/MCM9 variant carriers meeting the pathogenicity-based filtering criteria were identified in the SPS case group, fCRCX, and HMF (metastasized CRC and endometrial cancer case groups) cancer-specific cohorts." (PMID 40684266, 2025).
familial cancer (1 paper, 2020). "Finally, the presence of MCM8/MCM9 genetic variants in the independent analyzed cohort with a putative involvement in familial cancer/CRC predisposition supports, to some extent, our conclusions." (PMID 32841224, 2020).
germ cell tumor (1 paper, 2025). A benign or malignant, gonadal or extragonadal neoplasm that originates from germ cells. "Considering the prevalence of germ cell tumors in female biallelic MCM8/MCM9 variant carriers, annual ultrasound screening starting at age 10 could be considered, given the early onset of 11–15 years observed in our case series." (PMID 40684266, 2025). "Similarly, biallelic MCM8 variants should be considered in cases of unexplained germ cell tumors, especially when accompanied by recessive inheritance or hypogonadism." (PMID 40684266, 2025). "Three female carriers—two with biallelic MCM8 variants and one with a biallelic MCM9 variant—were diagnosed with germ cell tumors (HP:0100728) between the ages of 11 and 15 years." (PMID 40684266, 2025). "Moreover, our case series indicates that beyond hypogonadism, biallelic MCM8 and MCM9 variants are associated with early-onset germ cell tumors (occurring before age 15)." (PMID 40684266, 2025).
hypogonadism (1 paper, 2025). A disorder characterized by decreased function of the gonads. "Following the initial discovery of biallelic germline MCM8/MCM9 variants in families with CRC, polyposis, and hypogonadism, we present a comprehensive clinical and molecular characterization of biallelic MCM8/MCM9 variant carriers from multiple sources." (PMID 40684266, 2025). "Out of these 49 monoallelic MCM8 variant carriers, hypogonadism was noted in 14 (29%) individuals, with two having a likely pathogenic variant and 12 carrying a VUS." (PMID 40684266, 2025). "For instance, the c.482A>C [p.(His161Pro)] VUS in the MCM8 gene, previously linked to hypogonadism, was shared by six biallelic carriers across two families." (PMID 40684266, 2025). "Furthermore, osteoporosis or delayed bone age (HP:0000939) was reported in seven individuals with biallelic MCM9 variants and one individual with biallelic MCM8 variants, all of whom were affected by hypogonadism." (PMID 40684266, 2025). "The majority of individuals with biallelic MCM8 (23 out of 26, 88%) or MCM9 (26 out of 28, 93%) variants from our case series experienced hypogonadism (HP:0000815)." (PMID 40684266, 2025). "MCM8 and MCM9 are newly proposed cancer predisposition genes, linked to polyposis and early-onset cancer, in addition to their previously established association with hypogonadism." (PMID 40684266, 2025).